KCTD5 (potassium channel tetramerization domain containing 5)
Description:
Its interaction with CUL3 suggests that it may act as a substrate adapter in some E3 ligase complex.
Synonyms: FLJ20040
Tractability: PROTAC: ubiquitination databases record sites on it; its protein half-life has been measured.
Gene: Protein-coding gene on chromosome 16 (2,682,521 to 2,709,030, forward strand). Ensembl gene ENSG00000167977.
Subcellular location: Cytoplasm, cytosol; Cytoplasm; Nucleus
Gene Ontology:
Molecular function: identical protein binding; protein binding; protein-containing complex binding; cullin family protein binding
Biological process: proteasome-mediated ubiquitin-dependent protein catabolic process; protein homooligomerization
Cellular component: cytoplasm; cytosol; Cul3-RING ubiquitin ligase complex; nucleus
Genetic constraint (gnomAD): Loss-of-function variants: 10 observed, 21.82 expected, observed/expected ratio (o/e) 0.46, 90% interval 0.28 to 0.78. The synonymous counts are far from expectation, so gnomAD's model fits this gene poorly and the ratio says little. Missense variants: 199 observed, 227.65 expected, observed/expected ratio (o/e) 0.87, 90% interval 0.78 to 0.98. Synonymous variants: 131 observed, 102.49 expected, observed/expected ratio (o/e) 1.28, 90% interval 1.11 to 1.48.
Homologues: Orthologues: dog KCTD5 (97% identical), guinea pig KCTD5 (97% identical), mouse Kctd5 (96% identical), rat Kctd5 (96% identical), rabbit KCTD5 (94% identical), macaque KCTD5 (85% identical), tropical clawed frog kctd5 (82% identical), pig KCTD5 (54% identical), Drosophila melanogaster inc (53% identical), Caenorhabditis elegans inso-1 (47% identical), zebrafish KCTD5 (44% identical). Paralogues in human: KCTD2 (74% identical), KCTD17 (65% identical), KCTD9 (36% identical).
Diseases named in the same sentence as KCTD5 in open-access papers:
KCTD5 is named in the same sentence as 21 diseases in open-access papers, as found by Europe PMC text mining. Sharing a sentence is not in itself a finding about the gene and the disease. The quoted sentences say what the papers report.
breast carcinoma (5 papers, 2020 to 2025). "Previous studies have linked KCTD5 to advanced cancer stages and poor prognosis in colorectal cancer and breast cancers." (PMID 40832836, 2025). "Confirming these data, COSMIC and GENT2 db indicate KCTD5 overexpression in 12.5% of breast cancer samples (FC = 1.33, p-value < 0.001)." (PMID 34001146, 2021). "Both TRPM4 and KCTD5 mRNA expression was shown to be increased in triple negative samples, a more aggressive subtype of breast cancer that lacks specialized treatment, as well as in ER+/PR+ samples." (PMID 33562811, 2021). "Conversely, KCTD5 is overexpressed in breast cancer samples and is involved in the regulation of cell migration in a TRPM4-dependent manner." (PMID 33053687, 2020). "Indeed, KCTD5 is a negative regulator for the migration of melanoma and breast cancer cells, by affecting Rac1 activity and Ca2+ signaling." (PMID 34001146, 2021). "KCTD5 has been shown to correlate with particular classes of breast cancer." (PMID 33562811, 2021).
colorectal cancer (4 papers, 2023 to 2025). A primary or metastatic malignant neoplasm that affects the colon or rectum. "Potassium Channel Tetramerization Domain 5 (KCTD5) regulates diverse aspects of physiology, ranging from neuronal signaling to colorectal cancer." (PMID 37762619, 2023). "The PrognoScan survival analysis also revealed significant differences in OS between the high and low expression groups of KCTD5 in ovarian cancer (P = 0.002, HR = 5.68), follicular lymphoma (P = 0.013, HR = 0.65), colorectal cancer (P = 0.025, HR = 0.24), and melanoma (P = 0.027, HR = 0.39)." (PMID 37149576, 2023). "KCTD5 has been identified as having a role in cell migration 28, 29; and GET4, as part of a larger protein complex with BAG6, has been shown to play a role in the recruitment of BRCA1 to sites of DNA damage 30 and promote tumour growth in models of colorectal cancer." (PMID 37771787, 2023).
lung adenocarcinoma (3 papers, 2023 to 2024). A carcinoma that arises from the lung and is characterized by the presence of malignant glandular epithelial cells. "Real-time quantitative PCR and flow cytometry analysis were performed to determine the biological functions of KCTD5 in lung adenocarcinoma cells." (PMID 37149576, 2023).
lung carcinoma (3 papers, 2022 to 2025). "We also examined the level of apoptosis in lung cancer cell lines and the association between KCTD5 and apoptosis-related genes." (PMID 37149576, 2023). "Furthermore, we confirmed the involvement of KCTD5 in the regulation of lung cancer cell apoptosis in vitro." (PMID 37149576, 2023). "KCTD5 is a member of the KCTD protein family, and its role in lung cancer has not yet been reported." (PMID 35705627, 2022).
melanoma (3 papers, 2020 to 2023). A malignant, usually aggressive tumor composed of atypical, neoplastic melanocytes. "The obtained results suggest that Rac1 is involved in the higher migration and cell spreading linked to KCTD5 depletion in melanoma cells, such as a constitutively active Rac1 construct enhanced both cellular responses in control, but not in B16-F10kctd5-/- cells." (PMID 33053687, 2020). "Cullin3, via the adaptor protein KCTD5, also regulates cell adhesion and spreading in murine melanoma cells, suggestive of Rac1 activation." (PMID 34136490, 2021). "Together, our data indicate that KCTD5 is a negative regulator for the migration of melanoma cells by affecting two crucial molecular players of this process: Rac1 activity and Ca2+ signaling." (PMID 33053687, 2020). "Here, we provide novel data demonstrating that KCTD5 regulates cell migration, spreading, focal adhesion dynamics, Rac1 activity and intracellular Ca2+ levels of melanoma cells." (PMID 33053687, 2020). "In this study, we demonstrated that KCTD5 influences cell migration, cell spreading, and focal complexes and focal adhesion dynamics in a model of murine melanoma cells." (PMID 33053687, 2020). "To study whether KCTD5 is involved in migration, we used the highly migratory model of B16-F10 melanoma cells." (PMID 33053687, 2020). "While these authors reported that depletion of KCTD5 attenuates RhoGDI degradation in HEK293T cells, RhoGDI levels are unaffected when Cullin3 is silenced in human melanoma cells." (PMID 34136490, 2021).
glioma (1 paper, 2019). A benign or malignant brain and spinal cord tumor that arises from glial cells (astrocytes, oligodendrocytes, ependymal cells). "For example, VOPP1 and CDKN2A, which have been proved important in glioma, were linked by KCTD5 in GBM." (PMID 31719831, 2019).
lymph node metastasis (1 paper, 2022). "Subsequently, we analyzed the correlation between KCTDs gene expression level and clinicopathologic features, and we found that the expression of KCTD5 and KCTD21 was significantly higher in the lymph node metastasis group than in the normal group." (PMID 35705627, 2022).
morphine dependence (1 paper, 2024). Strong dependence, both physiological and emotional, upon morphine. "Taken together, the results demonstrated that CUL3/KCTD5 regulates morphine dependence via modulating the sensitization of AC in PVT." (PMID 39008526, 2024). "Another important finding of the present study is to uncover the roles of CUL3/KCTD5-mediated AC1 sensitization in morphine dependence." (PMID 39008526, 2024).
ovarian carcinoma (1 paper, 2023). A malignant neoplasm originating from the surface ovarian epithelium. "We found that ovarian cancer patients with high expression of KCTD5 had poor prognoses." (PMID 37149576, 2023).
cancer (7 papers, 2020 to 2025). A tumor composed of atypical neoplastic, often pleomorphic cells that invade other tissues. "We analyzed the association between KCTD5 expression and the level of infiltration by CAFs in pan-cancer." (PMID 37149576, 2023). "For instance, KCTD5 has recently been implicated in cancer biology, which may present an additional arena of exploration for prospective studies." (PMID 40233107, 2025). "Importantly, the relationships between KCTD5 expression and genomic mutations, prognosis, the immune microenvironment, cancer-associated fibroblasts (CAFs), and drug sensitivity were revealed." (PMID 37149576, 2023). "Moreover, KCTD5 expression was related to the immune microenvironment, infiltration by cancer-associated fibroblasts, and the expression of immune-related genes." (PMID 37149576, 2023). "Thus, our findings could help to elucidate new regulatory mechanisms involving KCTD5 as an inhibitor of processes associated with cancer metastasis." (PMID 33053687, 2020). "In the present study, we comprehensively analyzed KCTD5 gene across multiple databases as a basis for evaluating the molecular function of KCTD5 in pan-cancer and identifying its value in tumor prognostic prediction and drug therapy." (PMID 37149576, 2023). "Genetic alterations and DNA methylation of the KCTD5 gene across cancers were analyzed using the GSCA database." (PMID 37149576, 2023). "In conclusion, our first pan-cancer study of KCTD5 demonstrated that this gene is highly expressed in most cancers and revealed an association between KCTD5 expression and CNV, SNV, and DNA methylation." (PMID 37149576, 2023). "The function of KCTD5 in cancer development has been shown in increasing numbers of studies, but no comprehensive studies of its role in pan-cancer have been conducted." (PMID 37149576, 2023). "This study systematically investigated the expression landscape of KCTD5 across cancers through multiple databases." (PMID 37149576, 2023). "The immune landscape in pan-cancer suggests that KCTD5 plays an important role in regulating the tumor immune microenvironment." (PMID 37149576, 2023). "The results indicated that KCTD5 is highly expressed in most cancers and that its expression is significantly correlated with tumor prognosis." (PMID 37149576, 2023). "We assessed the prognostic value of KCTD5 in pan-cancer using the Kaplan–Meier plotter and the PrognoScan database." (PMID 37149576, 2023). "Our results suggest that KCTD5 is a potential molecular biomarker that can be used to predict patient prognosis, immunoreactions and drug sensitivity in pan-cancer." (PMID 37149576, 2023). "Subsequently, we performed a co-expression analysis on KCTD5 and immune-related genes (genes that encode or are related to immunoinhibitors, immunostimulators, MHC molecules, tumor-infiltrating lymphocytes, chemokines, and chemokines receptors) in pan-cancer." (PMID 37149576, 2023). "Furthermore, we measured the expression of KCTD5 in cells with different immune and molecular subtypes in pan-cancer." (PMID 37149576, 2023). "KCTD5 was expressed at a low level in the C3 subtype in all 10 cancers examined." (PMID 37149576, 2023). "We also evaluated the protein expression level of KCTD5 in pan-cancer (UALCAN database)." (PMID 37149576, 2023). "Therefore, our future efforts will focus on verifying the effect of the CUL3/KCTD5-mediated regulation of RhoGDI1 stability on cancer progression." (PMID 32876072, 2020). "Considering the cell models used here, it emerges the idea about the relevance of KCTD5 in cancer." (PMID 33053687, 2020). "In addition, we investigated heterozygous amplifications (CNV = 1) and heterozygous deletions (CNV = -1) of KCTD5 in various cancers and found that heterozygous amplifications occurred frequently in KIRP, BRCA, ACC, and KICH, while heterozygous deletions were more common in UCS, OV, BLCA, and LUSC." (PMID 37149576, 2023).
cancer (continued). "Emerging evidence has highlighted the significance of various gene families in cancer progression, including the KCTD family, comprising genes, including KCTD2, KCTD5, KCTD9, KCTD10, KCTD12, KCTD15, KCTD16, and KCTD21." (PMID 40832836, 2025). "We have extensively discussed the molecular function of KCTD5 in pan-cancer, but there is a lack of clinical validation." (PMID 37149576, 2023). "More and more studies have demonstrated that potassium channel tetramerization domain-containing 5 (KCTD5) plays an important role in the development of cancer, but there is a lack of comprehensive research on the biological function of this protein in pan-cancer." (PMID 37149576, 2023).
tumor (5 papers, 2021 to 2025). "In this study, the R package “UCSCXenaShiny” was used to analyze associations between KCTD5 gene expression and immune signatures/tumor immune cell infiltration in the TCGA database." (PMID 37149576, 2023). "The study evaluated the expression of KCTD5 in human tumors, as well as its prognostic value and its association with genomic alterations, the immune microenvironment, tumor-associated fibroblasts, functional enrichment analysis, and anticancer drug sensitivity." (PMID 37149576, 2023). "Previous studies have shown that KCTD5 is associated with tumor development." (PMID 37149576, 2023). "Furthermore, KCTD5 was significantly associated with the tumor immune microenvironment, programmed cell death, and drug sensitivity." (PMID 37149576, 2023). "In the future, we will further explore the key apoptotic signaling pathways and targets in the regulation of tumor apoptosis by KCTD5, providing a new theoretical basis for effective tumor therapy." (PMID 37149576, 2023). "This study systematically analyzed the expression landscape of KCTD5 in terms of its correlations with tumor prognosis, the immune microenvironment, programmed cell death, and drug sensitivity." (PMID 37149576, 2023). "Prior studies have indicated that KCTD5 is involved in ubiquitination processes that regulate cell cycle progression, which may explain its overexpression in OC and its role in promoting tumor growth." (PMID 40832836, 2025). "The findings may help elucidate the role of KCTD5 in tumorigenesis as well as offer new insights for tumor precision therapy." (PMID 37149576, 2023). "Our results preliminarily suggest that KCTD5 is involved in the regulation of tumor cell apoptosis, but the specific regulatory mechanism remains unclear." (PMID 37149576, 2023). "Thus, we propose a new question: does KCTD5 mediate tumor metastasis by regulating hypoxia-induced EMT?" (PMID 35705627, 2022). "KCTD5 may be used as a predictor of tumor response to chemotherapy." (PMID 37149576, 2023). "In conclusion, our study identified the expression pattern, clinical application value, immune infiltration and molecular function of KCTD family genes in LUAD, and KCTD5 as an important prognostic biomarker may be involved in the regulation of tumor progression mediated by hypoxic microenvironment." (PMID 35705627, 2022). "Interestingly, we also found that KCTD5 positively regulates tumor hypoxia signaling pathways." (PMID 35705627, 2022). "Further involvement of KCTD5 in other tumor types has not yet been described, but Brockmann and colleagues demonstrated that KCTD5 may switch off the Akt pathway, which regulates cell survival, cell cycle progression and cellular growth." (PMID 34001146, 2021).
infection (1 paper, 2017). The state of being infected such as from the introduction of a foreign agent such as serum, vaccine, antigenic substance or organism. "Interestingly, we found that KCTD5 levels decreased during infection in a CagA and VacA-independent manner." (PMID 29114497, 2017). "In addition, KCTD5 could interact with other scaffolding proteins to form E3 ligase complex during infection." (PMID 29114497, 2017). "Since we do not observe an increase in the ubiquitination of KCTD5 due to the infection with H. pylori, we cannot ruled out another ubiquitin-independent mechanism of proteolysis involved on the degradation of KCTD5." (PMID 29114497, 2017).
movement disorder (1 paper, 2025). Neurological conditions resulting in abnormal voluntary or involuntary movement, which may impact the speed, fluency, quality and ease of movement. "The dystonic epochs and coordination deficits observed in KCTD5 KO reflect hyperkinetic movement disorder pathology observed in patients with polymorphisms in signal transduction machinery, including DRD2, GNAL, GNAO1, and GNB1." (PMID 40233107, 2025).
KCTD5 also shares sentences with these, for which no sentence is quoted: brain cancer (1 paper); follicular lymphoma (1); glioblastoma (1); hepatocellular carcinoma (1); medulloblastoma (1); pancreatic adenocarcinoma (1); urinary bladder cancer (1); uterine corpus endometrial carcinoma (1).